ERBB2 (erb-b2 receptor tyrosine kinase 2)
Diseases named in the same sentence as ERBB2 in open-access papers (continued):
Sharing a sentence is not in itself a finding about the gene and the disease.
cancer (continued). "In vitro photoacoustic microscopy demonstrated significant uptake and contrast enhancement only in EGFR/ErbB2-positive cancer cells compared to benign cells after incubation with the nanoparticles." (PMID 37998152, 2023). "Although the present computational study provides two potential candidates for ErbB-2 amplified cancers, an experimental process needs to be established, a matter which is the theme of our future study." (PMID 36936983, 2023). "By the way, even though ErbB2 is overexpressed in a fraction of HNSCCs, its expression levels appear on the whole lower in this type as compared to other types of cancer." (PMID 36817764, 2023). "The claudin-low/non-ER-negative/HER2-negative group had a higher prevalence than claudin-low/ER-negative/HER2-negative cancers of amplifications in loci 11q13.3, 17q12 and 8p11.23, encoding for the genes CCND1, ERBB2 and NSD3, respectively." (PMID 37345027, 2023). "In specific cases, cancer cells originating from ER and HER2 double-positive tumors undergo ERBB2/HER2 amplification without significant downstream HER2 signaling activation." (PMID 37627192, 2023). "In normal mammary epithelial cells, LOXL2 overexpression induces oncogenic transformation and cancer progression by activating the Erb-B2 receptor tyrosine kinase 2 (ERBB2) through the production of reactive oxygen species (ROS)." (PMID 37762708, 2023). "Decreased PHLDA2 expression increases cell proliferation and reduces sensitivity to targeted agents in EGFR/ErbB2-driven cancer." (PMID 37575253, 2023). "Especially for patients with ERBB2-positive cancer, trastuzumab use increased 10-fold in China and surpassed that in the US since 2017." (PMID 37389867, 2023). "The TyrEx cycloaddition was applied to site-specifically label the therapeutically relevant Her2/ErbB2 Affibody protein with the DOTA chelator for use in cancer target radiolabelling." (PMID 37400596, 2023). "A significant (GeneRatio > 0.5) activation of critical pathways contributing to HER2 + cancer disease progression, including regulation of cell motility, chemotaxis, and neuron projection guidance, is observed in ERBB2 positive cells." (PMID 36598637, 2023). "We discovered that ERBB2+ cancer cells are enriched with poly U sequences on their 3’UTR which are mRNA-stabilizing sequences." (PMID 37359373, 2023). "Our research aimed to design novel anticancer chimeric suppressors of protein synthesis in ErbB2 -positive cancer cells by ricin, a natural toxic." (PMID 36936983, 2023). "Human epidermal growth factor receptor 2 (HER2) has proven to be an oncogene of increasing interest in these cancers, as HER2 protein overexpression and/or c-ERBB2 gene amplification ranges from ~30 to 35% in USC, and between ~15 and 20% in UCS." (PMID 37627113, 2023). "Associations were seen between ERBB2-low status and survival for stages II to IV TNBC and stages III to IV hormone receptor–positive cancer, although these differences were also small." (PMID 36821125, 2023). "The signaling cascade of ERBB2 is mediated by kinases and as such the resistance to anti-ERBB2 is concomitant with the increased activity of kinase that helps the drug-resistant cancers to proliferate and metastasize." (PMID 37359373, 2023). "At the same time, over-activating the ErBb2 gene triggers cancer cell metastasis and shows the anti-apoptotic behaviour of cancerous cells." (PMID 37845675, 2023). "The proportion of ERBB2-low diagnoses was lower at academic or research centers (61.8%) than at community cancer programs (66.5%), comprehensive community cancer programs (67.5%), or integrated network cancer programs (67.1%)." (PMID 36821125, 2023). "The morphology of the trastuzumab-resistant ERBB2+ cancer cells containing the destabilized elements shows shrinking and reduction in cell size compared to the controls." (PMID 37359373, 2023).
cancer (continued). "For these patients who have treatment-resistant cancers with an overexpression of ERBB2, there is limited clinical intervention for them." (PMID 37359373, 2023). "Overexpression or over-activation of ERBB receptor, especially ERBB2, has been found in many types of cancer and has been used as an important drug target for the development of anticancer therapy." (PMID 37324014, 2023). "Having established that the ERBB2-destabilizing constructs work and degrade the ERBB2 transcript and protein expression, we turned our attention to the devastating clinical problem of ERBB2+ trastuzumab-resistant cancers." (PMID 37359373, 2023). "drug category revealed that drugs with similar targets tend to be clustered together, and drugs targeting ErbB2, 3, and 4 were more potent in cancer cell lines with high ErbB2 expression as compared with drugs targeting EGFR (ErbB1) alone." (PMID 37508418, 2023). "Increased expression of the resistance genes ABCG2 and ERBB2, the CSC gene ALDH1A3, as well as the EMT gene SNAI1 after 5-FU treatment in PDSs were linked to ER-negative status of the primary cancer." (PMID 38124067, 2023). "On chromosome 17q12‐21, SMARCE1 is located closely to ERBB2 and both genes can be co‐amplified in cancer." (PMID 36916408, 2023). "The first group of genes was well-known cancer-related genes, i.e., Fgfr2, Hras, Tgfbr2, Nf1, and Erbb2." (PMID 37063417, 2023). "Whereas sapitinib has an enhanced pharmacologic profile due in part to equipotent inhibition of EGFR, erbB2, and erbB3, showing potent antitumor activity in preclinical cancer models." (PMID 36982163, 2023). "The newly identified genes included several well-known cancer drivers, such as Fgfr2, Hras, Tgfbr2, Nf1, and Erbb2, as well as others whose function in cancer remains elusive." (PMID 37063417, 2023). "We found that YES1 pT60 protein expression was decreased in the desARE3’UTR ERBB2-3 and -30 compared to the controls across multiple ERBB2-driven cancer types such as NC-H1975." (PMID 37359373, 2023). "Prompted by the important role of cholesterol metabolism and trafficking in the invasive capacity of ErbB2-driven cancer cells, we investigated the effect of p95ErbB2 expression on the entire lipidome by mass spectrometry-based shotgun lipidomics." (PMID 37420029, 2023). "We concluded that the CD19-4D5scFv fusion protein mediated the recognition of the human ErbB2+ cancer cells and finally their elimination by the activated CD19-CAR T cells." (PMID 36672182, 2023). "We compared the efficiency in targeting the ErbB2+ cancer cells by the CD19-4D5scFv redirected CD19-CAR T cells with those by the ErbB2-CAR T cells." (PMID 36672182, 2023). "HER2 overexpression as a result of ERBB2 amplification has been recognized as a driver alteration in multiple cancer types." (PMID 40028484, 2023). "Herceptin is a cancer-specific antibody that binds to the receptor tyrosine-protein kinase erbB-2 protein HER2/neu receptor present in breast cancer cells." (PMID 37650011, 2023). "These proof-of-principle findings strongly suggest that our destabilizing constructs do not affect normal cells but are cancer-specific and on target, which is very promising and only works in cancers carrying the stabilizing ERBB2 elements." (PMID 37359373, 2023). "We found that the degrading of the ERBB2 transcript by destabilized 3’UTR changed the cancer ERBB2 gene expression almost to near normal lung epithelial cell gene expression program." (PMID 37359373, 2023). "ErbB2 promotes cancer cell growth and glycolysis through the increased expression of lactate dehydrogenase isoform A (LDH-A)." (PMID 37109525, 2023). "Patients with higher levels of ERBB2 mRNA in their malignant plasma cells experienced significantly increased cancer mortality, shorter progression-free survival, and worse overall survival than other patients." (PMID 37373090, 2023).
cancer (continued). "Enriched pathways associated with cluster 2 include “Signaling by ERBB2 in Cancer” (Holm-adjusted p = 0.045), “PI3K events in ERBB2 signaling” (Holm-adjusted p = 0.013), and “GRB2 events in ERBB2 signaling” (Holm-adjusted p = 0.013)." (PMID 37546930, 2023). "Some of the most well-characterized RTKs implicated in cancer include the “HER family”, i.e., epidermal growth factor receptor (EGFR), ErbB2 (neu, HER2), ErbB3 (HER3) and ErbB4 (HER4), as well as VEGF/VEGFR, which is discussed in the following paragraphs." (PMID 38136430, 2023). "This is reasonable considering all genes are involved in related pathways such as Proteoglycans in cancer (ERBB2, TIMP3 and IGF2) and ECM–receptor interaction (COL6A2)." (PMID 38069080, 2023). "The six TM molecules analyzed all displayed bispecific binding to ErbB2 and UniCARs and selectively triggered UniCAR-NK cell cytotoxicity toward cancer cells expressing high or more moderate levels of the target antigen." (PMID 36688995, 2023). "For patients with ERBB2 (formerly HER2 or HER2/neu)-positive cancer, the proportion in China (30.2%) was higher than that in the US (15.6%)." (PMID 37389867, 2023). "ErbB2 is a well-studied oncogene whose role in cancer development has been well-established, and HER2 inhibitors have been developed and are used successfully in the clinic for treating tumors expressing high levels of HER2." (PMID 37508418, 2023). "We further selected 27 HER2-low TNBC cells on the basis of ERBB2 expression from the Genomics of Drug Sensitivity in Cancer database (between quartiles was considered HER2-low)." (PMID 37991016, 2023). "Prompted by our discovery showing that induced expression and activation of p95ErbB2 regulates genes involved in cholesterol uptake and trafficking, we studied if and how cholesterol uptake is involved in ErbB2-mediated cancer cell invasion." (PMID 37420029, 2023). "Overexpression of ERBB2 occurs in several forms of cancer, such as breast, stomach, colon, ovary, lung, head and neck, uterine serous endometrial carcinoma, esophagus, bladder, and uterine cervix, and it also serves as a predictive biomarker." (PMID 37108234, 2023). "Tyrosine kinase inhibitors such as osimertinib, erlotinib, and gefitinib target the ERRB/EGFR, and antibodies such as trastuzumab, which target the ecto-domain of ERBB2, have been developed as therapeutics such as ERBB2-overexpressing cancers." (PMID 37359373, 2023). "ErbB2-induced BLNK downregulation likely blocks the apoptotic form of death of detached cancer cells since we observed that ectopic BLNK triggers apoptosis symptoms in the cells, such as caspase-3 cleavage and Annexin V positivity." (PMID 35933456, 2022). "Among four members of the EGFR family members, EGFR and ErbB2 are best studied and known for their roles in cancer, so most drugs developed and under clinical trials are targeting these two receptors." (PMID 36438839, 2022). "In 1999, tanespimycin entered clinic as the first HSP90 inhibitor, and showed good therapeutic effect in various cancers either in single dose or in combinations, including melanoma, ERBB2‐positive metastatic breast cancer, refractory MM,395 and so on." (PMID 35928554, 2022). "In this study, we found that patients with ERBB2 amplification had higher TMB than non-ERBB2 amplification (p = 0.0024), which provided new evidence for the application of immunotherapy in ERBB2 amplification cancers." (PMID 35911441, 2022). "It was revealed that these signaling pathways possessed more prominent advantages in ERBB2 mutant cancer and progression-free survival." (PMID 36172165, 2022). "In most cases,increased HER2/neu expression in a cancer cell is due to an amplification ofthe ERBB2 gene located in the 17q12 locus of the chromosomeand associated with specific changes in some loci of other chromosomes (11q13,16q22–q24, and 18q21)." (PMID 35923562, 2022).
cancer (continued). "In ERBB2+ cancer cells, compound 14 reversibly enhanced trastuzumab inhibition of cells survival, inhibited cell migration, and induced cell cycle arrest in the G0/G1 phase." (PMID 35897965, 2022). "Taking some GCA patients as an example, ERBB2/EGFR is present as circular DNA in cancer cells and forms focal amplification." (PMID 35883211, 2022). "To estimate the number and characteristics of cancer classes on ERBB2 mRNA data, we used the g3mclass default parameters with varying bins (vector of k: 10, 15, 20, 25, 30, 35, 40)." (PMID 36335194, 2022). "The HER2/ERBB2/NEU gene, amplified in 15–35% of BC cancers, encodes a RTK that activates EMT as well as the repair of radiation-induced DNA damage." (PMID 35205744, 2022). "ERBB2 promoter demethylation increases transcript protein amplification and promotes a poor prognosis for cancer patients." (PMID 36172165, 2022). "The cancer subtypes with the most cases with ERBB2 CNG by NGS were breast (n = 67), non-small cell lung (n = 25), colorectal (n = 18), gastroesophageal (n = 17), pancreatic (n = 11), and uterine (n = 11)." (PMID 35126865, 2022). "HER3 has been shown to play a critical role in EGFR- and HER2-dependent cancers, including cancer cells harboring an EGFR mutation or amplification of the ERBB2 gene." (PMID 35249128, 2022). "Our study is the first comprehensive analysis of a large group of Chinese patients with pan-cancer, it has extended our understanding of ERBB2 fusions in solid tumors significantly." (PMID 36276102, 2022). "The overexpression of both Erbb2 and Erbb3 genes indicates an expression pattern that is common in both chronic wounds and cancer." (PMID 36009225, 2022). "ERBB2 and downstream PI3K signaling are thus clearly the drivers of cancer properties in this cell line, matching the clinical relevance of ERBB2/HER2 as the therapeutic target in this subtype." (PMID 35625984, 2022). "Given the complexity of amplification of Her2, it is critical to perform a pan-cancer analysis of the ERBB2 gene and estimate its correlation with survival of patients." (PMID 36172165, 2022). "Some studies have revealed that ERBB2 gene enrichment is a critical factor in the progression of cancers." (PMID 36172165, 2022). "These malignancies are typically treated with various ErbB2-targeted drugs, but many such cancers develop resistance to these agents and become incurable." (PMID 35933456, 2022). "Although all four ERBB receptors were implicated in cancer, only ERBB1, ERBB2, and ERBB4 have intracellular tyrosine kinase domains." (PMID 35765648, 2022). "This implies a defensive role for the ErbB2 receptor against oxidative stress, and thus suggests a possible induction of ErbB2 in stressed cancer cells, to defend themselves from oxidative damage." (PMID 35372019, 2022). "Somatic mutations of ERBB2 in the tyrosine kinase domain have been studied extensively, and play a role in response to anti-HER2 therapy among different cancer types." (PMID 36276102, 2022). "Lastly, the most significant Reactome signaling pathways with Benjamini–Hochberg correction and FDR < 0.001 were PIP3 activates AKT signaling, PI3K/AKT signaling in cancer, signaling by ERBB2, and MTOR signaling." (PMID 35773405, 2022). "Three canonical surface receptors have been identified as being critical biomarkers and significant in cancer signaling—the estrogen receptor (ER), the progesterone receptor (PR), and the receptor tyrosine protein kinase ErbB-2, commonly known as HER2." (PMID 35208277, 2022). "In this study, pan-cancer analysis highlighted the crucial role of ERBB2 in the immune microenvironment and metabolic remodelling." (PMID 35990657, 2022). "Based on the fact that PTPRO can sensitize cancer cells to different therapies, we overexpressed PTPRO in ERBB2-positive cancer cells and demonstrated that the overexpressed PTPRO is capable of reversing lapatinib-insensitivity." (PMID 35431974, 2022).
cancer (continued). "ERBB2 expression data were extracted from TCGA pan-cancer cohort and integrated using the Perl language." (PMID 35990657, 2022). "It was well-documented that ErbB2 is been widely investigated as an oncogenic marker and the predictor of cancer prognosis." (PMID 35322023, 2022). "Upon binding to neuregulin 1 (NRG1), ERBB3 preferentially dimerizes with HER2 (ERBB2), in turn inducing aggressive features in several cancer types." (PMID 35406375, 2022). "Somatic ERBB2 SNVs/indels occurred most common in bladder/urinary tract (7.3%) and intestine (6.1%) cancers." (PMID 35911441, 2022). "Our results provide important information on the activating mechanisms of ERBB2 extracellular domain (ECD) variants and illustrate a model workflow integrating wet and dry bench processes for the analysis of VUS detected with cancer gene panel tests." (PMID 34997908, 2022). "Bioinformatics analysis using the Cancer Cell Line Encyclopedia (CCLE) showed higher importin β1 message levels in TNBC than in ErbB-2-positive cells." (PMID 35534460, 2022). "GSEA was subsequently performed to examine the crucial role of ERBB2 in the immune and metabolic microenvironment of multiple human cancers." (PMID 35990657, 2022). "On chromosome 17q12, a well-known oncogene ERBB2 (HER2) coexisted with other cancer-related genes, such as CDK1240, STARD366, and GRB767." (PMID 36147475, 2022). "Five genes, AXIN2, BMP1, CR1, ERBB2, and RYR1, have been recorded of association with birth defects and cancer." (PMID 36384586, 2022). "In view of their drug mechanisms which bind to the HER2 kinase domain, pyrotinib or lapatinib can be a potential option for cancer patients with ERBB2 fusions, especially those X-ERBB2 fusions, which needs to be prospectively explored." (PMID 36276102, 2022). "To examine the biologic effects of ERBB2 E401G in cancer cells, we evaluated the proliferative and invasive capacities of H460 cells." (PMID 34997908, 2022). "The Spearman analysis showed that the crosstalk of the ERBB2 mutation among KICH and LGG primary tumors significantly correlated with some signaling pathways and played an indispensable role in distinct cancer cluster patterns." (PMID 36172165, 2022). "The other way around is true too, meaning that cancers with low ERBB2 mRNA expression possess increased ATM expression, as with the colon, kidney renal clear cell and kidney renal papillary cell." (PMID 36056635, 2022). "CDK12 was the most common co-amplification gene with ERBB2 in cancers with a high frequency of ERBB2 amplifications." (PMID 35911441, 2022). "This cohort study examines outcomes for patients with ERBB2-low metastatic breast cancer compared with those of patients with ERBB2-zero cancer." (PMID 36107428, 2022). "Based on the TCGA, GTEx, and FANTOM5 datasets, we analyzed the ERBB2 gene level of various cancer types." (PMID 36172165, 2022). "In this sense, the human epidermal growth factor receptor 2 (HER2, HER2/neu, and ErbB2) represents one of the most important targets for drug addressing or delivery in cancer therapy." (PMID 35889487, 2022). "ERBB2 (also known as HER2) receptor is a proto-oncogene frequently amplified and overexpressed in many human cancers." (PMID 35497981, 2022). "In view of the crucial role of ERBB2 in pan-cancer, a systematic analysis of the potential role of metabolic pathways enriched by HER2-coexpressed metabolites in pan-cancer is also an important undertaking." (PMID 35990657, 2022).